MTA1 (metastasis associated 1)
Diseases named in the same sentence as MTA1 in open-access papers (continued):
Sharing a sentence is not in itself a finding about the gene and the disease.
lung carcinoma (continued). "A systematic literature search was conducted to identify eligible studies which dealing with the relationship between MTA1 expression and prognosis of lung cancer in PubMed, Embase, Wanfang databases, China Biology Medicine disc and China National Knowledge Infrastructure." (PMID 29061215, 2017). "In addition, patients (n = 118) with early-stage lung cancer were enrolled in this study to confirm the correlations between MTA1 and EpCAM and pathoclinical parameters by using immunohistochemistry (IHC)." (PMID 26698569, 2015). "In addition, it was significantly positively associated with tumor diameter, clinical stage, and lymph node metastasis, suggesting MTA1 protein is engaged in the progression and aggression of lung cancer." (PMID 26698569, 2015). "We revealed a new molecular mechanism of MTA1-mediated invasion and metastasis in lung cancer through downstream target EpCAM, and interfering with EpCAM function may be a novel therapeutic strategy for treatment of MTA1-overexpressing lung carcinoma." (PMID 26698569, 2015). "Conversely, MTA1 knockdown in the three lung cancer cell lines suppressed EpCAM protein expression." (PMID 26698569, 2015). "Furthermore, we demonstrated that EpCAM promoted lung cancer cells invasion and migration, and the impaired tumor cell invasion and migration abilities following MTA1-silenging can be rescued by overexpressing EpCAM." (PMID 26698569, 2015). "In addition, a strong positive correlation was observed between MTA1 and EpCAM in IHC data, and MTA1 and EpCAM overexpression predicted poor prognostic in lung cancer cases." (PMID 26698569, 2015). "To confirm whether EpCAM mediates the effects of MTA1 on cell invasion and migration, we conducted the transwell invasion assay and wound healing assay in lung cancer cells." (PMID 26698569, 2015). "We checked the EpCAM expression by overexpressing or silencing MTA1 in lung cancer cells." (PMID 26698569, 2015). "Furthermore, these lung cancer cells with stably overexpressed or silenced MTA1 were transfected with siEpCAM or EpCAM-expressing plasmids and then subjected to western blot, invasion and migration assays." (PMID 26698569, 2015). "Therefore, the expression levels of this miRNA and MTA-1 could potentially function as prognostic biomarkers for patient outcome, recurrence and therapeutic response of patients with lung cancer." (PMID 30563114, 2018). "In addition, MTA1 knockdown could significantly inhabit the expression of miR-103, which might prohibit the invasive phenotype of lung cancer." (PMID 27167342, 2016). "Therefore, we hope that the results presented here may be helpful in the development of anti-metastatic strategies to potentially target the MTA1 alone or combined with EpCAM to inhibit the metastasis of lung cancer." (PMID 26698569, 2015). "Thus, this study was aimed to explore whether MTA1 was able to upregulate EpCAM expression and, consequently, modulate its effects on invasion and migration of the lung cancer cells as well as patients’ prognosis." (PMID 26698569, 2015). "While literature establishing a link between MTA1 and COX2 is sparse, one publication demonstrated a direct link between these biomarkers in human lung cancer." (PMID 40351767, 2025). "Different from our findings in lung cancer cells, in the present study, we provided evidence that MTA1 knockdown induced G1 arrest of NPC cells, suggesting that MTA1 promotes aberrant G1 to S phase transition, leading to increased proliferation and tumorigenicity of NPC cells." (PMID 23941622, 2013). "Overexpression of MTA1 could be a marker of poor prognosis in Chinese NSCLC patients, but not in lung cancer or small cell lung cancer." (PMID 29061215, 2017).
ovarian cancer (12 papers, 2012 to 2025). A primary or metastatic malignant neoplasm involving the ovary. "MTA1 is associated with advanced and metastatic ovarian cancer tissue." (PMID 40643517, 2025). "The elevated MTA1 levels seen in ovarian cancer in comparison to normal ovarian epithelium are in line with these findings." (PMID 40660330, 2025). "Increased levels of MTA1 were subsequently observed in ovarian cancer, and the overexpression of MTA1 can promote cell invasion and metastasis." (PMID 37894746, 2023). "The down-regulated protein level of MTA1 leads to the down-regulation of autophagy, apoptosis and invasion in ovarian cancer cells." (PMID 33282725, 2020). "IL-17 treatment possibly induced EMT in ovarian cancer cell lines via the expression of metastasis-associated genes-1 (MTA1) and targeting the IL-17/MTA-1 axis could be used as a treatment for ovarian cancer." (PMID 36766756, 2023). "Expression of MTA1 was found to be significantly enhanced in gynecological malignancies as breast or ovarian cancer tissues with advanced cancer stages and higher FIGO grading, indicating an important role of MTA1 in the progression of those tumor entities." (PMID 36689059, 2023).
gastric cancer (10 papers, 2008 to 2021). A primary or metastatic malignant neoplasm involving the stomach. "Cao24 reported that miR‐30c‐5p suppressed tumorigenesis and metastasis via MTA1 (metastasis‐associated protein 1) in gastric cancer." (PMID 31342628, 2019). "For example, in gastric cancer, miR-30c-5p suppresses migration, invasion, and epithelial to mesenchymal transition via targeting MTA1." (PMID 34572265, 2021). "IHC results showed a positive correlation between EIF5A2 and MTA1 expression in gastric cancers (P<0.001)." (PMID 25793713, 2015). "In gastric cancer, the expression of miR-30c-5p has been shown to be significantly reduced in cancer tissues, and it also suppresses both metastasis and epithelial-to-mesenchymal transition through targeting MTA1." (PMID 32977589, 2020). "EIF5A2 and its potential target metastasis-associated protein 1 (MTA1) expression were examined in 160 pairs of human gastric cancer and adjacent non-tumor specimens using immunohistochemistry (IHC) staining, and its correlation with clinicopathological features and survival was investigated." (PMID 25793713, 2015). "Many single biomarkers such as MTA1, TFF3, and CA72-4 were also reported to be related to the prognosis of gastric cancer with systemic therapy." (PMID 34245559, 2021).
nasopharyngeal carcinoma (10 papers, 2012 to 2025). A carcinoma arising from the nasopharyngeal epithelium. "In nasopharyngeal cancer, metastasis-associated protein 1 (MTA1) regulates IQGAP1 expression and promotes cell proliferation and motility." (PMID 34439095, 2021). "The prognostic value of metastasis-associated gene 1 (MTA1) in nasopharyngeal carcinoma (NPC) has been suggested." (PMID 23941622, 2013). "In nasopharyngeal cancer, MTA1-mediated metastatic promotion was mediated via hedgehog (Hh) signaling which influences various types of tumors." (PMID 40660330, 2025). "Meanwhile, we also verified the pro-oncogenic potential of MTA1 in nasopharyngeal carcinoma NPC and NSCLC progression and metastasis." (PMID 27533465, 2016). "FMNL1 increased cell aggressiveness in nasopharyngeal cancer by epigenetically upregulating MTA1." (PMID 36124068, 2022). "Inhibition of MTA1 downregulates PI3K signaling in a nasopharyngeal cancer cell line." (PMID 34439095, 2021). "The purpose of this study was to investigate the expression and prognostic value of MTA1 in nasopharyngeal carcinoma (NPC)." (PMID 22537306, 2012).
non-small cell lung carcinoma (9 papers, 2013 to 2025). A group of at least three distinct histological types of lung cancer, including non-small cell squamous cell carcinoma, adenocarcinoma, and large cell carcinoma. "It has also been indicated that MTA1 is correlated with tumor angiogenesis and poor outcome in patients with early-stage non-small cell lung cancer (NSCLC)." (PMID 24396455, 2014). "Previously, we identified miR-125b as a downregualted miRNA in non-small cell lung cancer (NSCLC) cell line upon MTA1 depletion." (PMID 23718732, 2013). "Furthermore, miR-125a-3p inhibits the proliferation and infiltration of non-small cell lung cancer cells by downregulating MTA1." (PMID 36144639, 2022). "The present study assessed the role of metastasis-associated protein 1 (MTA1) in epithelial to mesenchymal transition (EMT) and metastasis in non-small-cell lung cancer (NSCLC) cells using a normal lung epithelium cell line, three NSCLC cell lines, a mouse NSCLC model, and 56 clinical NSCLC samples." (PMID 28418915, 2017). "Several studies have demonstrated that miRNA-mediated targeting of MTA1 resulted in repression of EMT leading to diminished invasion and migration of human pancreatic, gastric, and non- small cell lung cancer." (PMID 40351767, 2025).
cervical cancer (8 papers, 2018 to 2025). A primary or metastatic malignant neoplasm involving the cervix. "A recent report evaluated the potential mechanistic link between metastatin-associated protein 1 (MTA1), whose levels are tightly associated with tumor progression in cervical cancer, and A3B in cervical cancer cells." (PMID 36560657, 2022). "MTA1 expression level has been associated with migration and invasion of cervical cancer cells." (PMID 31281798, 2019). "On the contrary, MTA1 was significantly upregulated in cervical cancer compared with normal cervical tissues (P < 0.05)." (PMID 36694148, 2023). "MTA1 and miR-661 expression were measured in 10 cervical cancer tissue samples and 10 corresponding normal cervical tissue samples." (PMID 36694148, 2023). "MTA1 gene expression was lower in normal cervical tissues than in cervical cancer tissues (P < 0.05)." (PMID 36694148, 2023). "We have also demonstrated that NuRD(MTA1) complex physically associates with PRMT5 to promote the EMT process and strongly induced bone metastasis in cervical cancer." (PMID 35534547, 2022). "This study demonstrates that the Snail/PRMT5/NuRD(MTA1) complex promotes the invasion and metastasis of cervical cancer in vitro and in vivo." (PMID 33953349, 2021). "Human cervical intra-epithelial neoplasia (CIN) and cervical cancer tissues had increased number of IL-17-positive cells and MTA1 expression compared to normal cervical tissues." (PMID 31281798, 2019). "Quantitative RT-PCR was used to analyze C/EBPβ (15 cervical cancer tissue samples and 15 corresponding normal cervical tissue samples), miR-661, and MTA1 mRNA expression in clinical samples (10 cervical cancer tissue samples and 10 corresponding normal cervical tissue samples)." (PMID 36694148, 2023). "However, MTA1, a metastasis related protein, was significantly overexpressed in cervical cancer tissues compared with normal cervical tissues." (PMID 36694148, 2023). "In the preliminary study of the mechanism of MTA1 promoting the invasion, metastasis and adhesion of cervical cancer cells, it was found that up-regulating the expression of MTA1 in HeLa cells could increase the expression of β-catenin." (PMID 33833775, 2021). "Among the potential targeting genes, SOST, MTA1, TFRC, and YAP1 are involved in some important signaling pathways modulating cervical cancer cell invasion, migration, and drug sensitivity." (PMID 30344797, 2018). "Inhibition of MTA1 and TGF‐β/ Smad reverses invasion and metastasis in cervical cancer." (PMID 40159638, 2025). "There was not a significant increase in MTA1 expression in C/EBPβ-overexpressing cervical cancer cells." (PMID 36694148, 2023). "We found little MTA1 staining and few IL-17A-positive cells in normal cervical tissues, however, MTA1 staining and number of IL-17A-positive cells were increased in CIN and cervical cancer tissues." (PMID 31281798, 2019). "C/EBPβ did not appear to signal through the MTA1 pathway in cervical cancer." (PMID 36694148, 2023). "In the human cervical specimens, we found that the number of IL-17-positive cells was positively correlated with MTA1 expression, suggesting that increased IL-17 expression in CIN and cervical cancer tissues may upregulate MTA1 expression, which facilitates neoplastic cell migration and invasion." (PMID 31281798, 2019).
colon cancer (8 papers, 2014 to 2025). "The colon cancer tissue array analysis revealed that cytoplasmic MTA1 is also significantly associated with tumor metastasis (p<0.001)." (PMID 24970816, 2014). "Additionally, MTA1 is an ATP synthase modulator, driving mitochondrial bioenergetic metabolism reprogramming associated with growth and liver metastasis of colon cancer." (PMID 41007909, 2025). "High‐throughput screening of an anticancer drug shows MTA1 knockout increases the sensitivity of colon cancer to mitochondrial bioenergetic metabolism‐targeted drugs and mTOR inhibitors." (PMID 37442756, 2023). "In this study, it was found that MTA1 levels are positively correlated with ATP5A levels and that MTA1 promotes mitochondrial energy production, thereby regulating colon cancer metastasis." (PMID 37442756, 2023). "Inhibiting ATP5A enhances the sensitivity of liver‐metastasized colon cancer to sirolimus in an MTA1‐dependent manner." (PMID 37442756, 2023). "Knockout of MTA1 increases the sensitivity of colon cancer to mitochondrial bioenergetic metabolism‐targeted drugs, mTOR inhibitors." (PMID 37442756, 2023). "MTA1 is a potential biomarker for evaluating the metastatic potential of colon cancer and predicting the sensitivity of tumors to certain metabolism‐associated drugs." (PMID 37442756, 2023). "To confirm the results derived from the TCGA COAD cohort, we performed a cytokine antibody array to detect cytokine secretion in HCT116 human colon cancer cells of the control group and MTA1-overexpressing group." (PMID 35350571, 2022). "The preliminary analysis of colon cancer cells and single-cell RNA-seq data revealed that high-level MTA1 tends to transform the function and quantity of macrophages into an immunosuppressive state." (PMID 35350571, 2022). "In conclusion, our results show that MTA1 overexpression in colon cancer drives a CD8+ T cell-rich but exhausted phenotype by decreasing macrophage intensity and inducing M2-like macrophage polarization." (PMID 35350571, 2022). "The noted inverse relationship between the levels of MTA1 and DNMT3a mRNAs was not limited to human breast or colon cancer but true for cancer, at-large, in general, when compared with the corresponding normal tissues using Oncomine dataset." (PMID 28393842, 2017). "For example, MTA1 and DNMT3a mRNA levels are significantly upregulated (p = 0.004) and downregulated (p = 3.00E-4) respectively, in gastric, renal, ovarian, skin and colon cancers when compared to the normal tissues." (PMID 28393842, 2017). "In colon cancer with low MTA1 expression, the cancer tissue is well differentiated, whereas in colon cancer with high nuclear MTA1 expression, the cancer tissue is poorly differentiated." (PMID 24970816, 2014). "Because MTA1 is up-regulated in cancers, we also investigated the distribution of MTA1 in colon cancer tissues." (PMID 24970816, 2014). "In addition to the downregulation of cytokines, the inflammatory stimulators IL-6 and SAA3P were also downregulated in MTA1-overexpressing CT26 mouse colon cancer cells." (PMID 35350571, 2022). "MTA1 was significantly higher in colon cancers than in their adjacent counterparts." (PMID 32901005, 2020). "Moreover, a higher frequency of mitotic defectiveness was detected in colon cancer samples with elevated MTA1 expression." (PMID 32901005, 2020). "Similar to normal colon tissues, MTA1 localizes to both the nucleus and cytoplasm in colon cancers." (PMID 24970816, 2014). "Thus, we immunostained a high-density colon cancer microarray, eliminated the invalid tissues, and subsequently scored the intensity of nuclear, cytoplasmic, and overall MTA1 analyses in each tissue." (PMID 24970816, 2014). "On the mesoscale dimension, we simulated that MTA1 directly interacts with complex I and complex V and verified that MTA1 promotes the activity of mitochondrial respiratory chain complex V, thereby supporting various energy metabolism‐related malignant behaviors of colon cancer." (PMID 37442756, 2023).
colon cancer (continued). "And then by colon cancer microarray analyses, we found a novel role of MTA1 in inhibiting cancer differentiation in the nucleus, and proposed that the nuclear and cytoplasmic components of MTA1 may drive cancer progression through different mechanisms." (PMID 24970816, 2014). "However, in colon cancer tissues with high cytoplasmic but low nuclear MTA1 expression (the overall MTA1 level is also high), the cancer tissue is still well differentiated, indicating an ineffective role for cytoplasmic MTA1 in the regulation of cancer differentiation." (PMID 24970816, 2014). "Our results suggest that mitochondrial MTA1 interacts with ATP5A, the α subunit of MAS, to promote ATP production and facilitate CRC cell proliferation and invasion, further contributing to colon cancer metastasis." (PMID 37442756, 2023). "To verify the clinical relevance of MTA1 and ATP5A expression in tumors from clinical patients, we analyzed the expression of cytoplasmic MTA1, ATP5A, mTOR, and p‐mTOR in tissues from colon cancer patients." (PMID 37442756, 2023). "We also noticed an inverse relationship between the levels of MTA1 and DNMT3a in NCI-60 Panel cell lines as well as in 59 breast and 61 colon cancer cell lines." (PMID 28393842, 2017). "The target cells used in this assay were SW620 colon cancer cells (HLA-A∗0201+, MTA1+) incubated with or without an anti-human HLA-A2 antibody and T2 cells pulsed with the corresponding peptide." (PMID 30596107, 2018).
lymph node metastasis (7 papers, 2012 to 2025). "MTA1 was found to be significantly associated with local invasion and lymph node metastasis." (PMID 34307133, 2021). "MTA1 is inextricably associated with depth of invasion (OR = 1.88, 95%CI: 1.05–3.37, P = 0.03), lymph node metastasis (OR = 2.33, 95%CI: 1.77–3.06, P<0.001), TNM stage (OR = 2.78, 95%CI: 1.63–4.74, P<0.001) and vascular invasion (OR = 2.22, 95%CI: 1.38–3.56, P<0.001) of GI cancers." (PMID 28570554, 2017). "Elevated expression of MTA1 was always associated with depth of invasion (OR = 2.60, 95%CI: 1.88–3.61, P<0.001), lymph node metastasis (OR = 2.17, 95%CI: 1.55–3.04, P<0.001), and TNM stage (OR = 2.54, 95%CI: 1.66–3.88, P<0.001), consistent with previous meta-analysis." (PMID 28570554, 2017). "Moreover, overexpression of MTA1 has been clinically linked to advanced clinical stage, lymph node metastasis and poor prognosis." (PMID 22537306, 2012). "Due to the limitation of the metastasis group sample size, future studies with a larger number of cases are needed to further examine the relationship between MTA1 and lymph node metastasis or distant metastasis." (PMID 33059651, 2020). "From a clinical perspective, MTA1 over-expression was strongly and independently correlated with depth of invasion, lymph node metastasis, vascular invasion and TNM stage." (PMID 28570554, 2017). "Significant higher TNM stage (p < 0.01), metastasis (lymph node metastasis and distant metastasis, p < 0.01) were observed in high-MTA1 expression group." (PMID 26689197, 2015). "MTA1 over-expression was strongly correlated with depth of invasion (OR = 1.88, 95%CI: 1.05–3.37, P = 0.03), lymph node metastasis (OR = 2.30, 95%CI: 1.76–3.01, P<0.001), vascular invasion (OR = 2.02, 95%CI: 1.40–2.91, P<0.001) and TNM stage (OR = 2.78, 95%CI: 1.63–4.74, P<0.001)." (PMID 28570554, 2017). "However, the clinical-pathological analysis revealed that positive MTA1 expression in RCCs was associated with the age of patients and T stage and grade but not with the lymph node metastasis." (PMID 33059651, 2020). "A similar result was shown in the no lymph node metastasis group, that is, MTA1-postive cases were more common than cases with negative MTA1." (PMID 33059651, 2020).